MTCO3P38 (MT-CO3 pseudogene 38)
Gene: Processed pseudogene on chromosome 3 (166,161,203 to 166,161,968, reverse strand). Ensembl gene ENSG00000242456.
Diseases named in the same sentence as MTCO3P38 in open-access papers:
MTCO3P38 is named in the same sentence as 2 diseases in open-access papers, as found by Europe PMC text mining. Sharing a sentence is not in itself a finding about the gene and the disease.
MTCO3P38 shares sentences with these, for which no sentence is quoted: hepatocellular carcinoma (1 paper); tumor (1).